RPL7P20 (ribosomal protein L7 pseudogene 20)
Synonyms: RPL7_8_636
Gene: Processed pseudogene on chromosome 5 (166,028,567 to 166,029,311, reverse strand). Ensembl gene ENSG00000254252.
Diseases named in the same sentence as RPL7P20 in open-access papers:
RPL7P20 is named in the same sentence as 1 disease in open-access papers, as found by Europe PMC text mining. Sharing a sentence is not in itself a finding about the gene and the disease. The quoted sentences say what the papers report.
gestational diabetes (1 paper, 2024). Carbohydrate intolerance first diagnosed during pregnancy. "Lastly, three new loci were significantly associated with gestational diabetes (top SNPs: rs72956265, rs10890563, rs79596863), located on or near ZBTB20, GUCY1A2, and RPL7P20, respectively." (PMID 38714721, 2024).